TLR1 (toll like receptor 1)
Diseases named in the same sentence as TLR1 in open-access papers (continued):
Sharing a sentence is not in itself a finding about the gene and the disease.
tumor (continued). "In our whole population-based study of NPC in Finland, we examined the expression of TLR1, TLR2, TLR4, TLR5, TLR7, and TLR9 in 150 tumours and analysed their pattern of expression according to EBV and HPV status, and clinical outcome." (PMID 31238894, 2019). "The target tumor cells were added to BMDMs activated by the following TLR agonists; TLR1/2 agonist Pam3, TLR2/6 agonist LTA, TLR3 agonist poly(I:C), TLR5 agonist flagellin, TLR7 agonist CL264, and TLR9 agonist CpG." (PMID 29123526, 2017). "Cell surface TLRs, including TLR1, TLR2, TLR4, TLR5, TLR6, and TLR10, can actively capture extracellular information, including tumor cell-released DAMPs or apoptotic cancer cell fragments, such as HMGB1, HSP, and S100, as well as extracellular vesicles containing changed cell components." (PMID 36911674, 2023). "Blocking TLR1/2 signaling significantly reduced the therapeutic efficacy of the immunogenic chemotherapeutic agent, resulting in reduced infiltration of DCs, CD4, and CD8 within the tumor microenvironment." (PMID 37945630, 2023). "In contrast, tumor regression was markedly reduced in the OXP/Pam3CSK4 group compared to mice that received OXP only, suggesting that activation of TLR1/2 signaling may enhance the therapeutic efficacy of OXP." (PMID 37945630, 2023). "It's worth noting that TLR1, TLR2, TLR3, TLR7, TLR8, and TLR9 were adversely connected with RNAss in the majority of cancers, but favourably correlated with RNAss in a very small number of tumours (KIRC, MESO, LAML, CHOL, KICH and THYM)." (PMID 35801728, 2022). "In addition, a synthetic bacterial lipoprotein (a TLR1/TLR2 agonist) was reported to reduce the suppressive function of Foxp3+ Treg cells and enhance the cytotoxicity of tumor-specific CTL." (PMID 35309296, 2022). "Activation of TLR1/2 heterodimers and TLR2/6 heterodimers in GAMs plays an important role in extracellular matrix remodeling and tumor expansion through induction of matrix metalloproteinases (MMPs), interleukin (IL)-6, and inducible nitric oxide synthase (iNOS)." (PMID 34715891, 2021). "Interestingly, systemic administration of a synthetic BLP, a TLR1/TLR2 agonist, to mice with established lung carcinoma, melanoma, or leukemia, led to tumor regression and a long-lasting protective response against tumor re-challenge." (PMID 29765907, 2018). "Several TLRs had significantly lower mRNA expression in the control versus NSCLC tumor tissue, namely TLR1,2,3,7,9, and 10 while TLR4,5,6 and 8 did not." (PMID 29190881, 2017). "TLR1 and TLR8 are preferentially expressed on tumor cells, and a high expression of TLR1 and TLR8 (mRNA and protein) was observed in cancer tissues, showing for the first time that TLR1 and TLR8 in humans may be related to CRC." (PMID 25547486, 2014). "Pam3CSK4, a TLR1/TLR2 ligand can induce tumor remission in severe combined immunodeficiency (SCID) mice by diminishing the suppressive function of Foxp3+ Treg cells and enhancing the cytotoxicity of tumor-specific CTLs." (PMID 22737174, 2012). "Considering that the expression of TLR1 signals the plasma membrane to the extracellular environment and that TLR3 is intracellular, variations in expression patterns may be related to the microenvironment and tumor development." (PMID 39208235, 2024). "As TLR1/2, TLR2/6, TLR4 and TLR5 are the most prominently expressed surface TLRs on NK cells, we investigated whether the co-activation of FcγRs with these TLRs would enhance the cytotoxic activity of NK cells, resulting in improved tumor cell killing." (PMID 34681717, 2021). "In our study, TLR family expression, specifically TLR1, TLR3, TLR4, and TLR6, was upregulated in BD3 tumors in comparison with low-grade budding tumors (both in patient and PDX tumors) suggesting the presence of TLR-mediated alterations in the tumor invasive front." (PMID 32719800, 2020).
cancer (32 papers, 2012 to 2025). A tumor composed of atypical neoplastic, often pleomorphic cells that invade other tissues. "On the other hand, cancer-associated toll-like receptor (e.g., TLR1-4) could be activated by mucosal bacteria, which would cause a carcinogenic process and oncogenic transformation through inducing inflammation." (PMID 28053372, 2016). "Indeed, aberrant TLR1, 2, 3, 4, 5, 6, and 9 signalling has been implicated in a variety of human cancers." (PMID 22013487, 2012). "The vast majority of studies regarding MDSCs and these innate receptors were conducted in the context of cancer and it has been shown that TLR1/2 agonists in MDSCs can act controversially." (PMID 39035356, 2024). "Studies have shown that TLR2, 4 and 9 are the three most important receptors that regulate the progression of various cancers among the TLR receptors (TLR1-10)." (PMID 37153547, 2023). "VCAN also induced IKKβ in primary murine BMDM, which were verified by microarray to overexpress > 10-fold over cancer cells TLR1, TLR2, TLR6-9, and TLR13." (PMID 36980752, 2023). "For the immune score, expression of TLRs was positively correlated with immune scores in almost all types of cancer, except TLR1 in UVM, TLR3, 4, and 5 in THYM, and TLR10 in DLBC." (PMID 35937402, 2022). "TLR1 was found in the cytoplasm of cancer cells in 146/149 (98%) samples, and TLR1 positivity was strong in 82% of all samples." (PMID 31238894, 2019). "Based on our results, TLR1/2/6-network is upregulated in Barrett's metaplasia, dysplasia, and cancer." (PMID 27008696, 2016). "While TLR3 levels were found to be significantly higher in dysplastic epithelial samples (P = 0.05, Student's t-test), TLR1 levels were found to be significantly lower in carcinoma epithelium (P = 0.01, Student's t-test)." (PMID 22013487, 2012). "Laser capture microdissection revealed an increase in TLR3 and a decrease in TLR1 mRNA levels in dysplastic and carcinoma epithelium, respectively." (PMID 22013487, 2012). "Similarly, Toll-like receptors (TLRs), particularly TLR1, TLR2 and TLR4, have been implicated in cancer development by modulating the tumor microenvironment and promoting inflammatory responses." (PMID 41254241, 2025). "TLR1 expression was significantly low in most types of cancers, except CHOL, GBM, and KIRC." (PMID 35937402, 2022). "In addition, for the stromal scores, the expression of TLRs was positively correlated with stromal scores in almost all types of cancer, except TLR1 in UVM and TLR3 in ACC, LAML, MESO, and READ." (PMID 35937402, 2022). "Upregulation of TLR1/2/6-network in Barrett's metaplasia, dysplasia, and cancer could mark improved recognition of bacteria by precancerous metaplastic and dysplastic cells leading to inflammation, which is one of the hallmarks of cancer." (PMID 27008696, 2016). "A total of 11 cancers displayed high expression, and seven cancers showed low expression of TLR1." (PMID 25547486, 2014). "We also show that TLR1 was significantly decreased in carcinoma epithelium and may represent the sole upstream TLR significantly affected in keratinocytes in late carcinogenesis." (PMID 22013487, 2012). "Furthermore, the CGGA database was used to confirm the prognostic function of TLR1 in this cancer." (PMID 34869584, 2021). "TLR1, TLR2, TLR3, TLR4, and TLR5 expression levels were high across the six immune subtypes in the pan-cancer data; TLR6, TLR7, TLR8, and TLR10 expression levels were moderate; and TLR9, TLR12P, and TLR8-AS1 expression levels were extremely low." (PMID 35801728, 2022). "Collectively, our data suggest that TAARD can induce NK cell IFN-γ production through TLR1-NF-κB and TLR3-STAT3 signaling pathways, rendering its potential use as an agent for cancer prevention or treatment." (PMID 30072983, 2018). "Expression levels of TLR1 and TLR6 showed decrease in carcinomas as compared with premalignant epithelium." (PMID 27008696, 2016).
cancer (continued). "There were strong TLR1 and TLR8 immunoreactivities in the cancer cells and in some inflammatory cells in the mucosa." (PMID 25547486, 2014). "In contrast, the increased TLR1 expression in malignant stroma is likely due to increased monocyte infiltration, implicating DAMPS from dying cancer cells as potential ligands." (PMID 22013487, 2012). "The GSEA revealed that cancer-related gene modules were remarkably enriched in patients with upregulated TLR4, TLR2, TLR1 and PYCR1 (TLR4upTLR2upTLR1upPYCR1up) compared with patients with a downregulated expression of these markers (TLR4downTLR2downTLR1downPYCR1down)." (PMID 41254241, 2025). "TLR3 was not up-regulated in any of the cancer tissues tested, whereas TLR1 was inversely up-regulated only in KIRC (P0.01), CHOL (P0.05), and GBM (P0.001)." (PMID 35801728, 2022). "Given this, we hypothesised that TLR1, TLR2, TLR3, TLR7, TLR8, and TLR9 would be involved in a negative regulatory mechanism mediated by TLR8-AS1 that contributes to the maintenance of cancer stem cell features." (PMID 35801728, 2022). "However, they did not observe significant increases in TLR2 expression in the subsequent progression to adenocarcinoma, with TLR1 and TLR6 showing decreased expression levels in carcinomas when compared with premalignant epithelium." (PMID 33922955, 2021). "We therefore tested whether recombinant IFN-β could synergize with two other TLR agonists, Pam3CSK4 (TLR1/2) and CL264 (TLR7) in inducing NO production and macrophage-mediated cancer cell growth inhibition by BMDMs." (PMID 30450098, 2018). "We identified Toll-like receptor 1 (TLR1), TLR2, TLR4 and TLR8 gene expression levels and downstream gene, i.e., interleukin-6 (IL-6), IL-8, interferon-α (IFN-α) and myeloid differentiation primary-response protein-88 (MyD88), expression levels in CRC patients and in cancer cell lines." (PMID 25547486, 2014). "TLR1 and TLR3 (Id:242667_at) exhibited reduced expression, and TLR4 (Id1552798_a_at) exhibited increased expression in individuals with cancer, independent of HPV (p < 0.05)." (PMID 39208235, 2024).
bacterial infection (26 papers, 2005 to 2026). "Thus, increased risk of invasive bacterial disease may be associated with decreased expression of an alternative BIRC6 transcript in TLR1/2-stimulated monocytes." (PMID 35866869, 2022). "Regardless, the STING1-MYD88 complex plays a major role in mediating ACOD1 expression during bacterial infection, especially in response to TLR1/2/4/5/6 signals." (PMID 35769880, 2022). "Although the main role of TLR-1 is to response to bacterial infection and participation in the resistance, we decided to check its possible effect of subchronic OAO-ASA administration on the carrageenan-induced inflammation." (PMID 27462270, 2016). "The positive selection inferred at site 559 of TLR1, adjacent to a site that leads to impairment of NF-kB activation, suggests a role for this site in regulating inflammatory response to bacterial infection." (PMID 25894218, 2015). "In this line, and according with our results, it has been shown a protective role for TLR1 during bacterial infection via its signaling in the intestinal epithelium." (PMID 25887178, 2015). "A chemical inhibition model of inflammation is proposed by semi-continuous monitoring the density of toll-like receptor 1 (TLR1) expressed on mammalian cells following bacterial infection to investigate an in vivo-mimicked drug screening system." (PMID 25136864, 2014). "TLR1 mRNA levels in kidney were remarkably up-regulated after the bacterial infection." (PMID 37056759, 2023). "TLR1 forms heterodimers with TLR2 and is activated in response to bacterial infections, during embryonic brain development or in neuropathogenesis." (PMID 35010941, 2021). "Activation of platelets with thrombin induces an important modulation of TLR1, TLR6, and TLR9 during vascular lesions potentially mediated by bacterial infection." (PMID 31781518, 2019). "The endometrial epithelial and stromal cell responses to lipopeptides via TLR2, TLR1, and TLR6 provide a mechanism linking a wide range of bacterial infections to inflammation of the endometrium." (PMID 24437488, 2014). "Existing literature suggests that TLR1 and TLR2 could play a significant role in the immune defense against bacterial infections." (PMID 39949364, 2025). "In addition, vitamin D3 plays an important role in LL-37 induction through Toll-like receptor 1 (TLR1) and TLR2 pathways during bacterial infection in monocytes and keratinocytes." (PMID 34445608, 2021). "Bacterial infection may also account for the previously reported constitutive high expression of TLR1, TLR2, TLR4, and TLR9 but not TLR3 in SGECs from SS patients." (PMID 32208441, 2020).
infectious disease (14 papers, 2009 to 2026). A disorder directly resulting from the presence and activity of a microbial, viral, or parasitic agent in humans. "Furthermore, the TLR1 rs4833095 polymorphism was found to affect the signaling functions of TLR1 in patients with infectious disease." (PMID 27806314, 2016). "Because of their essential roles in Mtb recognition process, polymorphisms in TLR-1, -2 and -6 are hypothesized to be associated with susceptibility to TB and other infectious diseases." (PMID 23691034, 2013). "Despite its reported association with TLR1, TLR2 variants are associated to a much wider panel of infectious diseases." (PMID 19924287, 2009). "TLR2/TLR1 as heterodimers has an important role in immune response in infectious diseases." (PMID 36313452, 2022). "Altogether, these previous findings and ours suggest functional immunophenotypes for TLR1 N248S and TLR6 P249S for infectious diseases." (PMID 31786695, 2020). "Notably, adaptive introgression and local positive selection led to the significantly increased expression of the TLR6, TLR1, and TLR10 genes, which facilitated resistance to infectious diseases but may also be associated with increased hypersensitivity to non-pathogenic allergens." (PMID 30930906, 2019).
cardiac disease (2 papers, 2018 to 2025). "Multiple genes known or plausibly linked to heart development and post-natal heart disease were found to be differentially methylated in the blood DNA of newborns with TOF including: ABCB1, PPP2R5C, TLR1, SELL, SCN3A, CREM, RUNX and LHX9." (PMID 30212560, 2018). "Therefore, it is likely that fibroblasts significantly contribute to the increased expression of TLR1, TLR3, and TLR7 and their downstream signaling pathways we previously observed in the myocardium of patients with cardiac disease." (PMID 39828779, 2025).
cardiovascular disease (2 papers, 2020 to 2025). "Given the important role of TLR and PAR in cardiovascular disease, one may speculate that the stronger inhibitory effects of ticagrelor on TLR-1/2 and PAR mediated platelet activation compared to prasugrel may at least in part contribute to the beneficial impact of ticagrelor on all-cause mortality." (PMID 32062795, 2020).
hematologic malignancies (1 paper, 2017). "The rs5743551 (−7202G>A) variation in the TLR1 gene, the rs7656411 (22215G>T) variation in the TLR2 gene and the rs11536889 (+3725G>C) variation in the TLR4 gene were genotyped in 365 recipients with hematologic malignancies and their unrelated donors in the discovery cohort." (PMID 28484092, 2017).
peripheral neuropathy (1 paper, 2022). A disorder affecting the peripheral nervous system. "Toll-like receptors (TLR-1, TLR-2, and TLR-4) and the transient receptor potential family of ion channels (TRPV1 and TRPV4) have been discovered, demonstrating their active role in chemotherapy-induced peripheral neuropathy." (PMID 35956877, 2022).
TLR1 also shares sentences with these, for which no sentence is quoted: Allergy (5 papers); allergic asthma (4); allergic rhinitis (4); rheumatoid arthritis (4); Autoimmunity (3); pneumococcal infection (3); adenocarcinoma (2); arthrosis (2); benign prostatic hyperplasia (2); bladder cancer (2); candidiasis (2); chlamydial infection (2); end-stage renal disease (2); hay fever (2); Multiple Myeloma (2); non-alcoholic fatty liver disease (2); respiratory disease (2); Stroke (2); ulcerative colitis (2); acute lung injury (1); acute monocytic leukemia (1); acute myeloid leukemia (1); acute pyelonephritis (1); Adenovirus infection (1); alopecia areata (1); Alzheimer disease (1); autoimmune thyroid disease (1); bacterial meningitis (1); Behcet disease (1); benign neoplasm (1).
A further 72 diseases each share a sentence with TLR1 in 1 paper.